NLRP3 (NLR family pyrin domain containing 3)
Diseases named in the same sentence as NLRP3 in open-access papers (continued):
Sharing a sentence is not in itself a finding about the gene and the disease.
diabetes (continued). "Research has shown that a variety of risk factors for CVDs, obesity, diabetes, and metabolic syndrome can activate NLRP3 inflammasome and promote inflammation." (PMID 35464402, 2022). "Activation of NLRP3 inflammatory vesicles is directly associated with the pathophysiology of chronic inflammatory diseases, such as diabetes, and its associated complications." (PMID 36589841, 2022). "Another study has demonstrated that diabetes aggravates myocardial I/R injury via influencing NLRP3 inflammasome-associated pyroptosis." (PMID 36238294, 2022). "In human cell models and in murine models of diabetes, hyperglycemia stimulated NLRP3 inflammasome activation, subsequently causing injury to pancreatic islet cells, glucose intolerance, and insulin resistance." (PMID 35719709, 2022). "Hyperglycemia caused by diabetes can directly cause pyroptosis, and the NLRP3 inflammasome is closely related to the pathogenesis of type 2 diabetes mellitus (T2DM)." (PMID 36232938, 2022). "Diabetes mellitus-associated endothelial dysfunction has been linked to NLRP3 inflammasome activation." (PMID 35889923, 2022). "The NF-κB inflammatory pathway promotes NLRP3 transcription, which in turn causes vascular dysfunction in diabetes." (PMID 35915611, 2022). "It was supported by our in vivo experiment clearly showing a loss of aggravated cystitis in diabetes by macrophage-depletion of NLRP3." (PMID 36405726, 2022). "The dysregulation of the best-characterized complex, the NLRP3 inflammasome, has been linked to the pathogenesis of diseases such as multiple sclerosis, type 2 diabetes mellitus, Alzheimer’s disease, and cancer." (PMID 35163573, 2022). "The expression of the different components of NLRP3 inflammasome in adipose tissue of obese individuals with type 2 diabetes mellitus is directly associated with body weight as well as with the severity of T2DM." (PMID 34070553, 2021). "They observed that cardiac disorders caused by diabetes in the rosuvastatin-treated group were prevented, while this effect was minimal in down-regulated NLRP3 rats." (PMID 32378144, 2021). "Previous studies have reported that diabetes and metabolic stress can cause the induction of pro-inflammatory cytokines through activation of nuclear factor kappa B (NF-κB) or the NLRP3 inflammasomes." (PMID 34071438, 2021). "Several studies have reported the crucial role of NLRP3 in atherogenesis and plaque destabilization in the association with diabetes." (PMID 34767557, 2021). "This analysis showed that serum deprivation led to robust activation of the NLRP3 inflammasome while diabetes-like stress caused a specific and dramatic induction of NF-κB." (PMID 34071438, 2021). "For example, NLRP3 deficiency prevents diabetes-associated vascular inflammatory damage and endothelial dysfunction." (PMID 33815662, 2021). "NLRP3-deficient C57BL/6 mice were also protected from diabetes development following STZ treatment, whereas ASC-deficient C57BL/6 mice were not." (PMID 34177937, 2021). "For instance, excessive or chronic activation of the NLRP3 inflammasome, an important innate immune sensor and inflammation regulator, and subsequent interleukin release are implicated in the pathogenesis of diabetes and pneumococcal pneumonia." (PMID 34876193, 2021). "Increasing evidence demonstrates that NLRP3 inflammasome is implicated in developing diabetes and associated complications." (PMID 35087834, 2021). "Aberrant mitochondrial ROS production caused by diabetes is critical for NLRP3 inflammasome activation via the oxidation of mitochondrial DNA." (PMID 33680286, 2021). "Overactivation of NLRP3 inflammasome has been linked to the pathogenesis of inflammatory bowel disease, cryopyrin-associated periodic syndromes, type 2 diabetes mellitus, atherosclerosis, and neurodegenerative diseases." (PMID 34835501, 2021). "Of note, NLRP3 inflammasome activation is an important pathogenic mechanism of diabetes and diabetic complications." (PMID 34512671, 2021).
diabetes (continued). "For other diabetic complications such as diabetic cognitive impairment, diabetic retinopathy, diabetes-associated fatty liver and so on, targeting NLRP3 inflammasome signaling is also proven to be an effective therapeutic approach." (PMID 34631209, 2021). "Visceral adipose tissue-derived serine protease inhibitor (vaspin) decreases NLRP3 levels in an autophagy-dependent mechanism in STZ-induced diabetes model, associated with the improvement of a systolic function." (PMID 35004869, 2021). "Pyroptosis induced by NEK7-dependent NLRP3 inflammasome activation is also critical in diabetes-associated periodontitis." (PMID 34177950, 2021). "The NLRP3 inflammasome has been implicated in the development of diabetes and neurodegenerative diseases." (PMID 34356130, 2021). "We found that RIPK3 deficiency attenuated diabetes-induced renal fibrosis, in association with reduced activation of the NLRP3 inflammasome." (PMID 32591618, 2020). "The inhibitory effect of gallic acid on NLRP3 inflammasome activation makes gallic acid an attractive new candidate for the treatment of NLRP3-associated diseases, such as diabetes, gout, and Alzheimer’s disease." (PMID 33365024, 2020). "Here, we demonstrated that mtDYN critically regulates the activity of the nutrient-sensing innate immunity-NLRP3 inflammasome pathway in diabetes-susceptible cybrid B4." (PMID 32849261, 2020). "Collectively, these data reinforce the idea that inflammation-related comorbidities such as comorbid stress and diabetes, drive NLRP3 inflammasome priming associated with worsening ischemic brain injury." (PMID 32466385, 2020). "Together, our data suggest that NLRP3 activation in endothelial cells promotes development of diabetes-associated AS." (PMID 32966239, 2020). "The aberrant activation of NLRP3 inflammasome has already been implicated in the pathogenesis of many diseases, including the diabetes." (PMID 31938471, 2020). "It would be inferred that LBE supplementation has protective effects on hyperglycemia-induced renal damage by activation of AMPK/SIRT1 along with reduced NLRP3 inflammasome-associated hyper-inflammation in diabetes." (PMID 32050658, 2020). "In another study, it was found that acid ceramidase (AC) deficiency significantly promoted the activation of NLRP3 inflammasome and the secretion of exosomes; the latter further promoted the release of IL-1β in the diabetes model." (PMID 32175320, 2020). "Accordingly, several studies have reported associations between the NLRP3 inflammasome and obesity, IR and type 2 diabetes mellitus (T2DM)." (PMID 32580621, 2020). "The present study shows that Nlrp3–/– mice are protected from diabetes-associated inflammatory vascular damage and endothelial dysfunction." (PMID 32009974, 2019). "To determine the involvement of NLRP3 in diabetes-associated vascular dysfunction, we used an NLRP3 inhibitor, MCC950." (PMID 31817997, 2019). "Our study highlights the importance of NLRP3 inflammasome in diabetes-associated vascular dysfunction, which is key to diabetes-associated complications." (PMID 32009974, 2019). "Pharmacologic inhibition or genetic deletion of the NLRP3 in mice protects from diabetes-associated inflammatory vascular damage and endothelial dysfunction." (PMID 32009974, 2019). "NLRP3 deficiency prevents diabetes-associated vascular inflammatory damage and endothelial dysfunction." (PMID 32009974, 2019). "NLRP3 deficiency prevented diabetes-induced decreased endothelium-dependent relaxation in mesenteric arteries (pD2, Nlrp3–/– T1D = 6.6 ± 0.1 vs. T1D = 6.2 ± 0.2; Rmax, Nlrp3–/– T1D = 80.8 ± 3.3 vs. T1D = 47.2 ± 4.9; P < 0.05)." (PMID 32009974, 2019). "Our study highlights the importance of NLRP3 inflammasome in diabetes-associated vascular dysfunction, which is key to diabetic complications." (PMID 32009974, 2019). "This study demonstrates the important role of NLRP3 inflammasome activation and its association with aldosterone in diabetes vascular dysfunction." (PMID 31817997, 2019).
diabetes (continued). "Targeting against the assembly and activity of the NLRP3 inflammasome is a potential and novel therapy for inflammasome-associated diseases, including ischemic stroke concomitant with diabetes." (PMID 31174550, 2019). "Pathological NLRP3 inflammasome signaling and IL-1β processing has been implicated in widespread conditions beyond diabetes and heart disease, such as gout, cancer and Alzheimer's disease." (PMID 29515457, 2018). "In this study, we treated cardiac fibroblasts with HG for 48 hrs to investigate the underlying mechanisms of the NLRP3 inflammasome in the progression of diabetes." (PMID 29314607, 2018). "Functionally Nlrp3 inflammasome has been implicated in the pathogenesis of various metabolic diseases, including obesity, diabetes, gout, silicosis, and acetaminophen-induced liver toxicity." (PMID 26980705, 2016). "The NLRP3 inflammasome has been implicated in the pathogenesis of various disorders like asbestosis, silicosis, gout, Alzheimer’s disease and diabetes, mostly through the production of IL-1β." (PMID 24915862, 2014). "The NLRP3 inflammasome has been shown to contribute to inflammatory processes, metabolic dysfunction and diabetes risk." (PMID 23924318, 2013). "Notably, the HMGB1/NLRP3 axis is also implicated in cognitive dysfunction associated with sepsis, diabetes, and Alzheimer’s disease." (PMID 40688353, 2025). "The precise relationship between CAPS2 (NLRP3) and diabetes is not yet fully understood; however, recent investigations suggest that NLRP3 and its associated inflammatory pathways may play a role in the pathogenesis of diabetes." (PMID 40296871, 2025). "Notably, overt activation of the NLRP3 inflammasome is associated with numerous autoinflammatory, autoimmune, and metabolic diseases including diabetes, Alzheimer's, and arthritis." (PMID 39327931, 2025). "Interestingly, in this animal model, the upregulation of FP receptor populations and increased force generated by FP receptor activation is driven by NLRP3-dependent inflammation associated with diabetes." (PMID 38682210, 2024). "Consequently, recent investigations into the management of diabetes mellitus and its associated complications have gravitated toward the exploration of NLRP3 inflammasome and NRF2." (PMID 38510357, 2024). "Here, we determine the role of NLRP3-mediated inflammation associated with diabetes in regulating prostaglandin signaling pathways responsible for bladder contractions using the diabetic Akita mouse model of UAB and Akita mice lacking the NLRP3 gene which fail to develop DBD." (PMID 38682210, 2024). "The P2X7-mediated NLRP3 pathway plays a pivotal role in cognitive impairments associated with various neurodegenerative conditions, such as Alzheimer’s disease, vascular dementia, and cognitive disorders linked to diabetes." (PMID 38256257, 2024). "The NLRP3 inflammasome is strongly linked between diabetes and AS." (PMID 38439031, 2024). "Indeed, the NLRP3 inflammasome and its associated pyroptosis are closely linked to key cardiovascular risk factors including hyperlipidemia, diabetes, hypertension, obesity, and hyperhomocysteinemia." (PMID 38681198, 2024). "Although many inflammasomes have been discovered to date, the NLRP3-mediated inflammasome has been well-studied because it senses a broad range of stimuli associated with various inflammatory diseases, including gout, diabetes, and rheumatoid arthritis." (PMID 37047051, 2023). "In conclusion, NLRP3 activation causes IL-1β release, increasing insulin resistance and reducing glucose uptake in target tissues such as liver and adipose tissue, leading to the pathogenesis of diabetes and obesity." (PMID 38069047, 2023). "NLRP3 activation results in increased caspase-1 activity, and IL-1β production, which drives expansion of pathogenic Th1 and Th17 cells and the induction of diabetes." (PMID 37081890, 2023).
diabetes (continued). "Development of new drugs targeting the NLRP3 inflammasome, IL-1 receptor antagonists, agents that can remove IL-1β from the circulation, etc., may reduce the susceptibility of diabetics to air pollution." (PMID 37919797, 2023). "The reduced anxiodepressive behaviors associated with diabetes produced by an inhibitor of the NLRP3 inflammasome, MCC950, supports this hypothesis." (PMID 37891874, 2023). "Also, NLRP3 functions in innate immune responses to pathogenic infection and metabolic stress relevant to systemic traits, such as diabetes and sepsis, as well as atherosclerotic lesion and stroke formations." (PMID 37082194, 2023). "To explore whether the WAT NLRP3 inflammasome/IL-1β pathway is related to higher diabetes risk factors in subjects with high-apoB, we used partial correlation analysis." (PMID 37914804, 2023). "Previous studies have shown that islet amyloid polypeptide (IAPP) is a protein formed in patients with diabetes that causes activation of the NLRP3 inflammasome, triggering a series of inflammatory responses that produce mature IL-1β, a process also known as glucose metabolism." (PMID 35647057, 2022). "As diabetes is a recognized risk factor for CKD, NLRP3 genes may be involved in diabetes-related CKD." (PMID 35428826, 2022). "Moreover, they can inhibit NLRP3-mediated inflammatory reactions to treat diabetes-associated complications." (PMID 35937790, 2022). "This means that NLRP3 inflammasome activation and the generation of correlative inflammatory factors in macrophages are closely associated with metabolic condition inflammation, especially in diabetes." (PMID 36142531, 2022). "Furthermore, the synergistic effect between FFAs and urate crystals leads to activating the NLRP3 inflammasome, suggesting that different metabolites associated with diabetes interact with each other to promote the development of inflammation." (PMID 35719709, 2022). "In recent years, a growing body of evidence suggests that inhibition of the NLRP3 inflammasome may slow pyroptosis in diabetes and associated complications." (PMID 35355717, 2022). "Calorie restriction and exercise-mediated weight loss decreased mRNA levels of NLRP3 and IL-1β, and improved insulin sensitivity in diabetic subjects, demonstrating that pyroptosis contributes to the pathogenesis of IR and diabetes by mediating inflammation and β-cell destruction." (PMID 36009329, 2022). "NLRP3 inflammasomes play an important role in diabetes-associated vascular dysfunction." (PMID 33815662, 2021). "We therefore speculated that NLRP3 inflammasome activation may be associated with stroke-induced retinal injury in diabetes." (PMID 34305534, 2021). "The statistical results of our study highlighted significant correlations between the GCF NLRP3 levels and serum glucose levels of the participating patients, in accordance with other studies on the topic of NLRP3 inflammasome, periodontal disease, and diabetes association." (PMID 34840527, 2021). "Moreover, pyroptosis which is also integrated to the NLRP3 inflammasome activation is associated with diabetes, hypertension, and hyperlipidemia." (PMID 33803178, 2021). "Studies indicate that lncRNAs and NLRP3 inflammasome are overexpressed in diabetes complications, implying that lncRNAs could cause inflammatory responses by activating NLRP3 inflammasome." (PMID 35087834, 2021). "Moreover, NLRP3 activation contributes to diabetes-associated vascular dysfunction and a proinflammatory phenotype." (PMID 33815662, 2021). "The NLRP3 inhibition may represent an optimal strategy to mitigate the impact of comorbidities associated with COVID-19 such as diabetes mellitus, hypertension, and obesity." (PMID 33193349, 2020).
diabetes (continued). "Next, the role of NLRP3 in endothelial cells in the development of diabetes-associated AS was assessed in endothelia-specific NLRP3 mutant, ApoE (-/-) mice (APOEKO/Tie2p-Cre/NLRP3MKO), compared to control ApoE (-/-) mice (APOEKO), supplied with either HFD, or normal diet (ND)." (PMID 32966239, 2020). "Next, the role of NLRP3 in endothelial cells in the development of diabetes-associated AS was assessed in endothelial cell-specific NLRP3 mutant, ApoE (-/-) mice (APOEKO/Tie2p-Cre/NLRP3MKO), compared to control ApoE (-/-) mice (APOEKO), supplied with either high-fat diet (HFD), or normal diet (ND)." (PMID 32966239, 2020). "We tested the hypothesis that mDNA contributes to diabetes-associated endothelial dysfunction and vascular inflammation via NLRP3 activation." (PMID 32009974, 2019). "Increased cardiovascular risk in CABG patients might increase the expression of NLRP3 inflammasome markers, since those patients often presented hypertension, diabetes and obesity, which have been associated with NLRP3 inflammasome activation." (PMID 30941060, 2019). "Notably, the inhibition of HMGB1 release by simvastatin resulted from the inactivation on NLRP3 inflammasome, which was associated with recovery of diabetes-induced vascular permeability." (PMID 29207644, 2017). "Aberrant activation of the innate immune system, including NOD-like receptor pyrin domain containing 3 (NLRP3) inflammasome-dependent interleukin-1β (IL-1β) secretion, has been implicated in the pathogenesis of type 2 diabetes mellitus (T2DM) and its complication." (PMID 28970837, 2017). "Moreover, caspase-1-dependent pyroptosis induced by ROS-mediated NLRP3 inflammasome activation is an important factor for the diabetes-associated increased sensitivity to MI/R and exacerbated MI/R injury." (PMID 29062465, 2017). "Additionally, we sought to determine the effect of TXNIP and elucidated its relationship to NLRP3 inflammasome activation in the susceptibility to ischemic AKI in diabetes." (PMID 27867451, 2016). "Obesity, diabetes, smoking, and age‐related immune system decline are associated with COVID‐19 disease severity and mortality and may contribute to hyperinflammation through continuous activation of the NLRP3 inflammasome." (PMID 41459687, 2026). "In diabetes, hyperglycemia may activate the NLRP3 inflammasome,causing apoptosis of retinal cells." (PMID 40758602, 2025). "Increasing numbers of studies have shown that the nucleotide-binding oligomerization domain-(NOD-) like receptor (NLR) protein 3 (NLRP3) inflammasome pathway is implicated in diabetes mellitus (DM) and DR." (PMID 36430950, 2022). "Therefore, considering the essential role that the NLRP3 inflammasome plays in DCM, targeting the NLRP3 inflammasome pathway might be a plausible treatment to reduce the risk of developing heart failure in diabetes." (PMID 34948026, 2021). "Moreover, our data support that MFG-E8 deficiency impairs wound closure and vascularization, and enhances inflammation with NLRP3 inflammasome activation in wound site of diabetes, and diabetes could prime MFG-E8-deficient neutrophils to undergo NETosis." (PMID 32963812, 2020). "Mesenteric resistance arteries from control (db/m) and diabetic (db/db) mice treated with vehicle, spironolactone (MR antagonist) or an NLRP3 selective inhibitor (MCC950) were used to determine whether NLRP3 contributes to diabetes-associated vascular dysfunction." (PMID 31817997, 2019).